ENOPH1 (enolase-phosphatase 1)
Description:
Bifunctional enzyme that catalyzes the enolization of 2,3-diketo-5-methylthiopentyl-1-phosphate (DK-MTP-1-P) into the intermediate 2-hydroxy-3-keto-5-methylthiopentenyl-1-phosphate (HK-MTPenyl-1-P), which is then dephosphorylated to form the acireductone 1,2-dihydroxy-3-keto-5-methylthiopentene (DHK-MTPene).
Synonyms: MASA; E1; mtnC; MST145
Tractability: Small molecule: a structure with a bound ligand is known. PROTAC: ubiquitination databases record sites on it; its protein half-life has been measured.
Gene: Protein-coding gene on chromosome 4 (82,430,589 to 82,461,177, forward strand). Ensembl gene ENSG00000145293.
Subcellular location: Cytoplasm; Nucleus
Subcellular location (Human Protein Atlas): Nucleoplasm; Nuclear bodies; Nucleoli
Pathways (Reactome):
Metabolism: Methionine salvage pathway
Gene Ontology:
Molecular function: acireductone synthase activity; protein binding; magnesium ion binding
Biological process: S-adenosylmethionine cycle
Cellular component: cytosol; cytoplasm; nucleus
Genetic constraint (gnomAD): Loss-of-function variants: 12 observed, 26.52 expected, observed/expected ratio (o/e) 0.45, 90% interval 0.29 to 0.73. The upper end of that interval is the gene's LOEUF score, 0.73, which puts it in group 3 of 6, group 1 being the genes least tolerant of losing a copy. Missense variants: 216 observed, 299.26 expected, observed/expected ratio (o/e) 0.72, 90% interval 0.64 to 0.81. Synonymous variants: 114 observed, 117.99 expected, observed/expected ratio (o/e) 0.97, 90% interval 0.83 to 1.13.
Homologues: Orthologues: chimpanzee ENOPH1 (100% identical), macaque ENOPH1 (99% identical), dog ENOPH1 (95% identical), mouse Enoph1 (93% identical), rat Enoph1 (92% identical), pig ENOPH1 (91% identical), guinea pig ENOPH1 (90% identical), rabbit ENOPH1 (89% identical), tropical clawed frog enoph1 (66% identical), zebrafish enoph1 (61% identical), Caenorhabditis elegans F58H1.3 (40% identical), Drosophila melanogaster Enoph (38% identical).
Diseases named in the same sentence as ENOPH1 in open-access papers:
ENOPH1 is named in the same sentence as 13 diseases in open-access papers, as found by Europe PMC text mining. Sharing a sentence is not in itself a finding about the gene and the disease. The quoted sentences say what the papers report.
colon cancer (2 papers, 2021). "Through lasso regression analysis, we selected seven optimal RNA construction models, namely, AGAP3, NHSL1, ENOPH1, NRG1, SNHG16, hsa-mir-1271-5p, and hsa-mir-26b-5p, to predict the prognosis of patients with colon cancer." (PMID 34692670, 2021). "Although not significant, mRNA expression levels of ENOPH1, RANBP1 and EIF4E were higher in BRAFV600E mutant colon cancer than in the unaltered group." (PMID 34201061, 2021).
Cerebral ischemia (1 paper, 2016). Restriction of arterial blood supply to the brain associated with insufficient oxygenation to support the metabolic requirements of the tissue. "We have obtained preliminary data showing that cerebral ischemia induces ENOPH1 mRNA expression in ischemic cerebral microvessels in a rat model of middle cerebral artery occlusion (MCAO)." (PMID 27630541, 2016). "In this study, we demonstrated a new role of ENOPH1 in mediating BBB injury under OGD conditions, which is a model of cerebral ischemia." (PMID 27630541, 2016).
glioma (1 paper, 2021). A benign or malignant brain and spinal cord tumor that arises from glial cells (astrocytes, oligodendrocytes, ependymal cells). "The expression of ENOPH1 was found to be increased in gliomas, while inhibition of ENOPH1 significantly reduced cell proliferation and cell migration." (PMID 34692670, 2021).
ischemia (1 paper, 2016). A hypoperfusion of the BLOOD through an organ or tissue caused by a PATHOLOGIC CONSTRICTION or obstruction of its BLOOD VESSELS, or an absence of BLOOD CIRCULATION. "Our data show that both in vivo and in vitro ischemia induce ENOPH1 upregulation in cerebral microvascular endothelial cells." (PMID 27630541, 2016). "In this study, we applied in vitro cultured brain microvascular endothelial monolayer and oxygen-glucose deprivation (OGD) to mimic the BBB and ischemia, respectively, and explored the role of ENOPH1 in ischemic BBB damage." (PMID 27630541, 2016).
ischemic stroke (1 paper, 2016). A stroke disorder caused by obstruction of blood flow to the brain, due to thrombotic (local blood clot formation) or embolic (due to a blood clot or other material traveling from another site) event. "As the first study, here we investigated the role of ENOPH1 in ischemic stroke with a focus on the BBB." (PMID 27630541, 2016). "In conclusion, our data demonstrate that ENOPH1 activation may contribute to OGD-induced endothelial cell death and BBB disruption through promoting ROS generation and the activation of apoptosis associated proteins, thus representing a new therapeutic target for ischemic stroke." (PMID 27630541, 2016).
virus infection (1 paper, 2016). "ADI1 is a downstream molecule of ENOPH1 in methionine salvage pathway and has been shown to be implicated in cell apoptosis, cell growth inhibition, oxidoreductase reaction and virus infection." (PMID 27630541, 2016). "ADI1 is a downstream protein of ENOPH1 and has been shown to play an important role in cell apoptosis, oxidoreductase reaction and virus infection." (PMID 27630541, 2016).
cancer (1 paper, 2022). A tumor composed of atypical neoplastic, often pleomorphic cells that invade other tissues. "The results of immunohistochemistry (IHC) in the Human Protein Atlas (HPA) database showed that compared with normal tissues, ENOPH1, ACAT1, ALDH4A1, FAS, and ASPG are downregulated in cancer tissue than in normal tissue." (PMID 35992263, 2022).
ENOPH1 also shares sentences with these, for which no sentence is quoted: infection (2 papers); Anxiety (1); breast carcinoma (1); neurodevelopmental disorder (1); Obesity (1); Sepsis (1).